IL10 (interleukin 10)
Diseases named in the same sentence as IL10 in open-access papers (continued):
Sharing a sentence is not in itself a finding about the gene and the disease.
infectious disease (continued). "Future research needs to elucidate whether these effects of variation in the IL-10 gene are exerted directly through its role in the repair of muscle tissue or indirectly through its role in the defence against infectious diseases." (PMID 25040424, 2014). "Recent studies have shown an increase in IL-10 in some infectious diseases." (PMID 23824716, 2013). "The correlation between IL-10 and cortisol observed in this study may indicate higher stress levels and more exposure to infectious disease in free-ranging porpoises." (PMID 23866055, 2013). "When looking at the anti-inflammatory cytokine profile, participants with infectious diseases showed high levels of INF-Υ and IL-10." (PMID 39328992, 2024). "IL-10, PCT, and PCT have been shown to have an essential role in infectious disorders, which is consistent with this study's findings." (PMID 35937269, 2022). "The major phenotypes identified in infectious diseases include CD28-negative CD39-positive CD8+ T cells in HIV infection, and the upregulation of the inhibitory receptor PD-1 on IL-10-secreting cells has also been observed in HIV, HBV and HCV." (PMID 36558866, 2022). "In this context, the macrophage migration inhibitory factor (MIF) and the interleukin-10 (IL-10) cytokines may operate as a molecular “Yin-Yang” in the modulation of the host immune microenvironment during African trypanosome infection, and possibly other infectious diseases." (PMID 35464430, 2022). "As the important mediators of negative regulation, anti-inflammatory cytokines such as IL-10 and TGF-β play important roles in maintaining the balance between protective immunity and the development of immune pathology in the context of infectious disease." (PMID 27525278, 2016). "Therapeutically, IL-10 can be specifically targeted to either attenuate or activate NLRP3 inflammasome in the treatment of several autoinflammatory and infectious diseases." (PMID 26412089, 2015). "Although no specific IL-10-based drugs are currently available for the treatment of infectious diseases, various existing drugs indirectly modulate IL-10 levels or activity." (PMID 38251210, 2024). "Even though some protein levels might be masked by drug treatment, data analysis showed high levels of INF-Υ, IL-10 and TNF-α in the infectious disease group, critical cytokines for the immune response against viruses and bacteria." (PMID 39328992, 2024). "The authors also highlighted that therapeutic strategies that increase the IL-10 and reduce the concentration in TNF-α could be used as adjuvants for treatment of such tissue injuries, as well as for infectious diseases." (PMID 30564201, 2018). "There is a growing body of evidence suggesting that the relationship between IL-10 and Th1 cytokines is not as antagonistic as originally believed, and infectious diseases appear to act in a complementary form." (PMID 26495323, 2015). "IL-10 and TGF-β are two potent immunosuppressive cytokines, which act via distinct pathways to modulate excessive immune responses and immunopathology in allergy, autoimmunity, and infectious disease." (PMID 23109946, 2012). "However, using IL-10 as a therapeutic agent is still being investigated, and no specific IL-10-based drugs are currently approved for clinical use in infectious diseases." (PMID 38251210, 2024). "There is an increasing body of evidence suggesting that the relationship between Th1 cytokines and IL-10 is not as antagonistic as it was first believed, and that these cytokines may complement each other in infectious diseases." (PMID 23824716, 2013). "Furthermore, the detection of an IL-10-to-IL-6 ratio greater than 1 in the vitreous and greater than 0.72 in the cerebrospinal fluid is considered useful for differentiating between PVRL and intraocular infectious diseases, and PCNL from intracranial infections, respectively." (PMID 33146828, 2021).
infectious disease (continued). "In infectious disease controls, a similar pattern was observed, but without correlations between DLL1 and MIF and IL-10." (PMID 38502427, 2024).
cardiovascular disease (71 papers, 2011 to 2026). "Both decreased and increased levels of anti-inflammatory cytokine (IL-10) play roles in the risk of developing cardiovascular diseases." (PMID 40564110, 2025). "As an anti-inflammatory cytokine, interleukin 10 plays an important role in systemic inflammation and associated processes, such as cardiovascular diseases." (PMID 39199367, 2024). "Conversely, we have also found IL-10 c-aAb to be associated with increased risk of cardiovascular disease in a cohort of kidney transplant recipients, again emphasizing the highly context-specific impact of c-aAb." (PMID 39606243, 2024). "It is well known that IL-10 is an important inflammatory suppressor in the body and is implicated in the development and progression of cardiovascular diseases." (PMID 37811136, 2023). "Baseline circulating levels of the anti-inflammatory IL-10 are positively associated with risk of cardiovascular disease." (PMID 35743792, 2022). "The increased IL-10 level is associated with reduced kidney function and increased risk of cardiovascular disease." (PMID 36249802, 2022). "The increased level of IL-10 has also been observed associated with inflammation in various cardiovascular diseases." (PMID 31886288, 2019). "IL-10 is a potent anti-inflammatory cytokine that plays a significant role in cardiovascular health, particularly in older adults, who often experience chronic inflammation and associated cardiovascular disorders." (PMID 39519510, 2024). "In line with the hypothesis concerning its anti-atherogenic properties, an increased IL-10 level has been associated with a better prognosis after cardiovascular disease." (PMID 39199367, 2024). "Lastly, IL-10 still plays a controversial role during T. cruzi infection; it is an anti-inflammatory cytokine, yet an elevated serum IL- 10 concentration is associated with fibrotic changes and cardiovascular disease." (PMID 35720419, 2022). "Understanding the role of IL-10 in regulating immune responses and inflammation is essential for developing therapeutic strategies aimed at mitigating the progression of cardiovascular diseases and improving patient outcomes." (PMID 39408157, 2024). "We also chose to quantify the immunoregulatory cytokines, IL-10, which has shown strong potential as a therapeutic target and IL-1RA, an antagonist of IL-1 even if its therapeutic application in cardiovascular diseases remains unproven." (PMID 39337629, 2024). "We first assessed CAEC pro-inflammatory cytokine production for IL-6, TNF-α, IL-18 and IL-1β, which are four important players for the development of cardiovascular diseases together with the anti-inflammatory cytokine IL-10." (PMID 36992409, 2023). "On the contrary, anti-inflammatory cytokines, such as interleukin-10 (IL-10) and adiponectin, which decelerate senescence and protect arteries against cardiovascular disease, seem to be downregulated with increasing age." (PMID 32582337, 2020). "Literature data have evidenced the association of the IL-10 and TGF-β SNPs with sporadic TAA and other cardiovascular diseases." (PMID 24707114, 2014). "Klotho may also reduce the expression of pro-inflammatory factors and may be important in the Klotho-IL-10-eosinophils pathway in patients with cardiovascular diseases." (PMID 41574188, 2025). "However, till now, such an association was only confirmed in patients with established cardiovascular disease (CVD), whose low Klotho concentrations accompanied low IL-10 levels." (PMID 36362746, 2022). "Although S1008A was also viewed as inflammatory, emerging studies indicate that S1008A has anti-inflammatory effects through scavenging ROS, reducing oxidative damage, and promoting IL-10 expression, beneficial for the regression of cardiovascular diseases and resolution of inflammation." (PMID 35418110, 2022).
cardiovascular disease (continued). "Whether IL-10 interferes with these pathophysiological mechanisms may become a therapeutic modality for other cardiovascular diseases in the future, and this requires further research." (PMID 35528508, 2022). "Excitingly, interleukin (IL)-10 in cardiovascular disease has been widely studied." (PMID 35433865, 2022). "Furthermore, the percentages of peripheral CD4 + CD25 + Foxp3 + Treg and serum IL-10 level were influenced by diabetic complications such as cardiovascular diseases." (PMID 29051757, 2017). "Lower concentrations of IL-10 may impair the resolution of inflammation in vascular tissues, leading to prolonged and chronic inflammatory responses that contribute to the enhanced atherosclerosis and the progression of cardiovascular diseases." (PMID 39408157, 2024). "Treg, with the secretion of anti-inflammatory IL-4, IL-10, and TGF-β, has been generally recognized as the crucial CD4+ T cell for the balance of systemic inflammation and relevant cardiovascular diseases." (PMID 36678161, 2023). "A case–control study with a designated experimental group of 110 patients with histories of cardiovascular disease (CVD) showed that s-Klotho levels were significantly lower in the CVD group and inversely correlated with CRP and TNFα/IL10." (PMID 35603960, 2022). "Studies have shown that main neuroactive cytokines involved in hypothalamic inflammatory mechanisms related to cardiovascular diseases are TNF-α, IL-6, IL1-α/IL-1β, and IL-10." (PMID 33967677, 2021). "As we identified some hub genes in the HBP family that were closely related to the development of disease, namely, IL10 and F2, we may reasonably suggest that these HBP family members can be further targeted for the diagnosis and prognosis of cardiovascular diseases in clinical practice." (PMID 32612856, 2020). "There wasno statistically significant difference between IL-8, IL-10, IL-13, TGF-1,in CKD patients with and without cardiovascular disease (p> 0.05)." (PMID 33711092, 2021).
kidney disease (52 papers, 2010 to 2026). "For instance, polymorphisms in the IL10 gene can be associated with complications of kidney diseases in children." (PMID 40725812, 2025). "The polymorphisms rs1800871 and rs1800896 in the gene encoding IL10 can be associated with the development of complications of kidney diseases in children." (PMID 40725812, 2025). "Based on this, the aim of our study was to assess the functional relationship of this IL-10 gene polymorphism with HUS outcomes in a valuable cohort of 17 infant patients with different severities of kidney disease." (PMID 37425258, 2023). "IL-6 and TNF-α have been determined to display high expression in CKD while the abnormal expression of IL-10 is also implicated as a risk factor for kidney disease." (PMID 35496058, 2022). "In renal cells, transient or persistent abnormal IL-10 expression is linked to TGFβ stimulus to promote fibrosis and progression of kidney disorders." (PMID 34769064, 2021). "The link between the risk of kidney diseases and the IL-10 -1082 A/G polymorphism has been explored before." (PMID 34090357, 2021). "Recently, several studies interpreted the link between the IL-10 -1082 A/G polymorphism and risk of kidney diseases." (PMID 34090357, 2021). "Serum IL-10 in the two groups of patients before treatment was significantly lower than that in the control group, suggesting that the activity of kidney disease is associated with immunoregulatory defects, and hormone can inhibit the secretion of IL-10." (PMID 33817188, 2019). "On the other hand, the analysis of clinical characteristics showed that high IL-10 producers carriers of the Atg5 T* allele presented significantly lower prevalence of cytopenia and a trend of less renal disorder compared with the other genotypes." (PMID 24205307, 2013). "Similarly, IL‐10 has been implicated in a myriad of renal diseases through its activation of anti‐inflammatory responses, immune regulation, and mitigation of renal tissue fibrosis." (PMID 41573378, 2026). "Therefore, in renal disease, further studies are needed to clarify that the decrease in IL-10 is the cause or results of the disease." (PMID 33817188, 2019). "This peak spans the IL10 gene, previously reported as being associated with T1D and kidney disease." (PMID 29444168, 2018). "Several novel drug delivery systems containing IL‐10 have shown promise in improving clinical outcomes in renal diseases." (PMID 41573378, 2026). "IL-10 is an anti-inflammatory factor that is secreted by immune cells, and it can improve the prognosis of kidney diseases through mechanisms such as activating anti-inflammatory responses, regulating immune responses, and reducing renal tissue fibrosis." (PMID 40824899, 2025). "Clinical studies are needed to explore the role of IL-10 immunotherapy in secondary kidney disease prevention." (PMID 38892418, 2024). "Some authors have also suggested that the ability of MSCs to treat kidney diseases is partly mediated by IL-10." (PMID 37895955, 2023). "IL-10 is a multifunctional immune regulator in diverse inflammatory diseases, including kidney disease." (PMID 35601837, 2022). "IL-10 can inhibit kidney disease in lpr mice through preventing IFNγ-mediated production of IgG2a, a major immune deposit in the kidney of these mice." (PMID 28697806, 2017). "BVRA regulates IL-10 expression in GM-CSF, M-CSF or LPS treated macrophages, indicating that BVRA is a potential target of kidney diseases via its effect on the IL-10 pathway in macrophages." (PMID 26393580, 2015). "Donizetti-Oliveira reported that ASC treatment prevents renal disease mostly because of the inflammatory response which increases the expression of anti-inflammatory factors IL-4, IL-10." (PMID 24260375, 2013). "However, theregulatory mechanism among these responses is unclear, as research on the effectof IL-10 on different kidney diseases mainly focuses on in vitro and animalexperiments." (PMID 38808074, 2024).
kidney disease (continued). "IL-10 acts as the anti-inflammatory and anti-fibrotic cytokines in kidney disease." (PMID 39262432, 2024). "The dysregulation of IL-10 is related to a variety of kidney diseases." (PMID 36762194, 2023). "The anti-inflammatory effect of ARB could be more potent than that of ACEis; for example, ramipril, an ACEi, increases IL-1β and IL-10 in patients with kidney diseases." (PMID 35517809, 2022). "On the other hand, increased IL-10 might impair the function of those cells and thus might explain the worsened kidney disease in MRL-FaslprKSRP−/− mice." (PMID 34831390, 2021). "As we detected also increased numbers of B cells in the kidney of MRL-FaslprKSRP−/− mice, this could also be the source of increased IL-10 production leading to enhanced autoantibody production responsible for worsening of kidney disease." (PMID 34831390, 2021). "Dogs from all groups of renal diseases showed elevated expression of IL-1α, IL-1β, IL-10, TGF-β and iNOS, a pattern that may therefore be considered the signature for canine renal disease." (PMID 26824356, 2016). "Reduced IL10 levels have also been reported in human kidney disease." (PMID 26734008, 2015). "In conclusion, the BVRA positive macrophage is a source of anti-inflammatory cytokine IL-10 in injured kidney, which may provide a potential target for treatment of kidney disease." (PMID 26393580, 2015). "Our data also demonstrates significantly higher levels of serum IL-10 in patients with specific organ disease in SLE, including musculoskeletal activity, renal disease, serositis and serological activity." (PMID 27708376, 2016). "In addition, levels of IL-1α, IL-1β TNFα, INFγ, IL-2 and IL-10 were elevated in the sera of CKD compared to sham, suggesting that the chronic state of renal disease affects the inflammatory network." (PMID 29889834, 2018). "The role of IL10 in LES is controversial, it has been considered as an anti-inflammatory mediator, but some studies demonstrate that the administration of IL10 accelerates the onset of renal disease, high serum levels of IL10 are found in patients with SLE and correlates with the disease activity." (PMID 23799000, 2013).
kidney (49 papers, 2010 to 2025). "In a cohort of 200 kidney transplant recipients, an imbalance of circulating follicular helper T cells (cTfh) over IL10+ Breg leads to graft failure." (PMID 40264774, 2025). "They showed that transduction of the IL-10 gene enhanced renal function and improved allograft survival in a rat model of kidney allograft rejection." (PMID 41303166, 2025). "Previous studies found that the activation of the PI3K/Akt signaling pathway during liver ischemia-reperfusion injury, increased IL-4, and IL-10 expressions, decreased IL-1β and TNF-α expressions, and reduced the hepatic inflammatory response." (PMID 36835571, 2023). "This was based on our previous finding that IL-10 was critical for the immune regulatory and cytoprotective effect of the Gsk3β pharmacological inhibitor in liver IRI." (PMID 36422999, 2023). "Markers of kidney inflammation, such as TNFα, IL1β, IL10, F4/80, MCP-1, and CRP, were assessed in total kidney tissues, isolated from both APN-KO and control mice." (PMID 33904399, 2021). "Here we got similar results as a recent study that hippocampal and serum levels of TNF-α, IL-1β, IL-6 were elevated accompanied by a drop in IL-10 level 24 h after middle cerebral artery occlusion in rats." (PMID 32848589, 2020). "Upon analysis, expression of the cytokines IFNB1, IFNG (IFN-γ), TNF (TNF-α), TGFB1 (TGF-β), IL1B, IL2, IL6, CXCL8 (IL-8), and IL10 were all significantly increased in ‘mesenchymal’ lung ADC compared to ‘epithelial’ tumors." (PMID 29440769, 2018). "In a recent study, renal DCs attenuated cisplatin-induced kidney inflammation by producing a high level of IL-10 in response to cisplatin treatment." (PMID 27172902, 2016). "As expected, increased kidney IR injury was observed in Il10−/− mice, as measured by BUN levels and ATN." (PMID 26035380, 2015). "Administration of IL-10 agonist reduces mortality of acute lung injury in rabbits with acute necrotizing pancreatitis, possibly through inhibiting proinflammation and strengthening host immunity." (PMID 24899788, 2014). "In addition, kidney injury-related indicators were positively correlated with IL-17 levels but negatively correlated with IL-10 levels, suggesting that immune balance is synchronized and associated with renal IRI." (PMID 36246554, 2022). "IL-10 plays a role in reducing alcoholic liver injury and inflammation." (PMID 30052665, 2018). "On the other hand, IL-10, an anti-inflammatory cytokine, was demonstrated to reduce liver IRI." (PMID 23750267, 2013). "Future investigation may clarify whether IL-10-driven IL-4Rα-independent MMR+Ym1+ macrophages have important functions in the control of liver granulomatous inflammation." (PMID 20502521, 2010). "In the process of kidney injury, M1 macrophages promote inflammation and tubular cell apoptosis by secreting pathogenic factors such as IL-1β, TNF-α and IL-6; however, M2 macrophages reduce inflammation and promote renal recovery by secreting trophic factors such as IL-10, TGF-β and arginase-1." (PMID 38785317, 2024). "In addition, IL-6 contributed to the anti-inflammatory effect, suggesting that it suppressed age-related fatty degeneration of the liver, in line with previous findings that exercise-induced IL-6 might have an anti-inflammatory effect because it induces IL-10." (PMID 38999780, 2024). "We compared markers of kidney inflammation and injury (neutrophil gelatinase-associated lipocalin, kidney injury molecule-1) as well as plasma and urine levels of T cell-associated cytokines (TNF-α, interferon-γ, interleukin (IL)-2, IL-4, IL-6, IL-8, IL-9, and IL-10) between groups." (PMID 36938084, 2023). "Oolong tea down regulated IL-6 and up regulated the expression of IL-10 to alleviate alcoholic liver injury, while white tea down regulated TNF-α and IL-6 and up regulated IL-10." (PMID 35677547, 2022).